MYCN (MYCN proto-oncogene, bHLH transcription factor)
Diseases named in the same sentence as MYCN in open-access papers (continued):
Sharing a sentence is not in itself a finding about the gene and the disease.
neuroblastoma (continued). "For instance, our analysis of MYCN-NA neuroblastoma identified two gene expression signatures that correlated with lower predicted tumor purity." (PMID 32275708, 2020). "MYCN-amplified neuroblastoma is characterized by significant clinical heterogeneity, which cannot entirely be explained by genetic differences." (PMID 33199677, 2020). "MYCN signalling disorders leads to a variety of tumours, including neuroblastoma, medulloblastoma, rhabdomyosarcoma, Wilms tumour, prostate cancer and lung cancer." (PMID 32660514, 2020). "Each gene set sheds light on biological themes that are differentially expressed within the MYCN-NA neuroblastoma cohort." (PMID 32275708, 2020). "The inhibition of BET proteins affects transcriptional regulation of several oncogenes, including MYCN inducing cell cycle arrest and apoptosis in preclinical models of neuroblastoma with MYCNampl." (PMID 32971811, 2020). "In line with our model of tissue-specific enhancer co-amplification, MYCN amplicon structure differed between medulloblastomas and neuroblastomas." (PMID 33199677, 2020). "Here we present a computational pipeline to discover cell-surface immunotherapeutic targets in MYCN amplified neuroblastoma." (PMID 32211329, 2020). "Consistent with the literature, MYCN-amplified neuroblastoma cell lines showed very high levels of N-Myc, MYCNOS, and IGF2BP1 and very low levels of c-Myc RNA expression." (PMID 31690716, 2019). "Here, we identified one novel tumor suppressor, α-N-catenin (CTNNA2), a cell adhesion molecule, silenced in some non-MYCN amplified neuroblastomas, correlated to low event-free survival probability." (PMID 31489113, 2019). "To identify the potential role of MYCN in FA metabolism regulation, we first used GC-MS to profile the medium- and long-chain FA landscape after MYCN depletion in the MYCN-amplified neuroblastoma cells IMR32." (PMID 31856871, 2019). "Downregulation of Sirt-2 reduces MYCN gene expression and results in apoptosis in a neuroblastoma cell line." (PMID 30713602, 2019). "High expression of survivin correlates with the advanced stage and MYCN amplification in neuroblastoma." (PMID 30609639, 2019). "In about 20–25% of neuroblastomas, poor prognosis has been directly correlated with MYCN oncogene amplification, which has been shown to orchestrate rapid progression and therapy resistance." (PMID 30691436, 2019). "One of the best examples of this is in neuroblastoma, where MYCN amplification is present in approximately 25% of neuroblastoma patients and disproportionally represents high-risk cases." (PMID 31616462, 2019). "Transgenic mice where the human MYCN cDNA is placed in front of the tyrosine hydroxylase promoter (Th-MYCN) spontaneously develop neuroblastomas which are morphological and phenotypical similar to human high-risk neuroblastomas." (PMID 30760980, 2019). "NVP-BEZ235 went on to demonstrate growth inhibition of neuroblastoma cells via suppression of MYCN both in vitro and in vivo." (PMID 35582571, 2019). "Lin28B indirect regulation of MycN expression by downregulation of Let-7 pre-miRNAs correspond well with a model that neuroblastoma is initiated by aberrant regulation of key developmental proteins." (PMID 30760980, 2019). "Micronuclei have been shown as a mechanism of elimination of genetic material, such as amplified MYCN genes from neuroblastoma cells (The MYCN gene is a cellular proto-oncogene of the MYC family of transcription factors)." (PMID 31086101, 2019).
neuroblastoma (continued). "Together, these results demonstrate that restoration of CTNNA2 expression is an advantageous strategy for in vivo neuroblastoma growth inhibition and tumor angiogenesis suppression in non-MYCN-amplified tumors, but less effective in MYCN-amplified tumors." (PMID 31489113, 2019). "Both quarfloxin and CX-5461 are cytotoxic to neuroblastoma cells in nanomolar concentrations and orally administered CX-5461 represses the growth of MYCN-amplified neuroblastoma xenografts in mice." (PMID 30542116, 2019). "Consistently, analysis of primary neuroblastoma samples demonstrated that MYCN-amplified cases showed a higher level of ASCL1 expression than nonamplified cases." (PMID 31819055, 2019). "The activity of MP1, a pyrrolomycin, was studied in MYCN amplified neuroblastoma (NB) alone and combined with temsirolimus (TEM)." (PMID 31455317, 2019). "This analysis revealed strong associations between the neuroblastoma lincRNAs MIAT and MEG3 and MYCN and PHOX2B activity or expression." (PMID 30952905, 2019). "It was discovered that an amplification of the MYCN (v-myc myelocytomatosis viral related oncogene, neuroblastoma derived (avian)) gene in Neuroblastoma patients was correlated with an increased aggressive behavior of the tumor, leading to a poor prognosis." (PMID 31167408, 2019). "The FNIII14-induced decrease in N-Myc protein was reproducible in other human MYCN-amplified neuroblastoma cell lines, such as NB-1 cells and KELLY cells." (PMID 31452837, 2019). "Amplification of the MYCN oncogene correlates with aggressive neuroblastoma growth, and we thus investigated putative correlations between MYCN and PIM isoform expression levels." (PMID 31310053, 2019). "Of all seven known DHA synthesis and transporter genes, the decrease of ELOVL2 expression was mostly significant in MYCN amplified neuroblastoma." (PMID 31856871, 2019). "Bioinformatics analysis showed that a lncRNA, which we named lncNB1, was one of the most overexpressed transcripts in MYCN-amplified neuroblastoma cell lines." (PMID 31690716, 2019). "Amplification of the MYCN gene on chromosome 2 is the most common genomic alteration in neuroblastoma, occurring in approximately 20% of patients, and is highly correlated with advanced disease stage and a poor prognosis." (PMID 30626019, 2019). "The other RNAs considerably over-expressed in MYCN-amplified neuroblastoma cell lines were RP11-102F4.3, RNF217, GRIK3, and SLCO5A1." (PMID 31690716, 2019). "ELOVL2 inhibited cell proliferation and the colony formation of MYCN-amplified neuroblastoma cell lines and mice xenografts, demonstrating that ELOVL2 suppresses critical malignancy processes." (PMID 31856871, 2019). "Subsequent studies showed that LMO1 overexpression significantly accelerates the latency, penetrance, and metastatic potential of MYCN-induced neuroblastomas in a zebrafish transgenic model." (PMID 31819055, 2019). "In the field of neuroblastoma, MYCN amplification status, the strongest indicator of poor prognosis and aggressive behaviour, has been analysed using cfDNA." (PMID 31817150, 2019). "In the present study, we examined the concordance of droplet digital PCR (ddPCR, in combination with immunohistochemistry, IHC) with FISH for MYCN detection in a panel of formalin-fixed paraffin-embedded (FFPE) human neuroblastoma samples." (PMID 30691436, 2019). "Amplification of the proto-oncogene MYCN, a known transcriptional activator of TERT, occurs in roughly 20% of primary neuroblastomas and is a well-established marker for defining high-risk disease." (PMID 31757062, 2019).
neuroblastoma (continued). "In summary, this study identifies a cytotoxic effect of 4-hydroxychalcone in MYCN-amplified human neuroblastoma cells, which rationalizes its further study in the development of new therapies for pediatric neuroblastoma." (PMID 31885773, 2019). "Taken together, RNA polymerase I inhibitors are promising agents that should be further investigated in clinical studies as a treatment options for neuroblastoma patients with high expression of MycN or c-Myc." (PMID 30542116, 2019). "MYCN, the key developmental transcription factor deregulated in neuroblastoma, has been shown to be a Wnt target gene in chicken limb mesenchyme." (PMID 31040767, 2019). "In both ATRX-inactivated and ATRX-wild-type neuroblastomas bearing ALT activation, elongated telomeres were detected, which was associated with poor outcome in non-MYCN-amplified neuroblastoma." (PMID 31757062, 2019). "The novelty of the present study is the use of unique human neuroblastoma PDXs that are MYCN amplified to evaluate the effects of FAK inhibition on neuroblastoma cells in vitro." (PMID 31519958, 2019). "In this study, we demonstrate a strong correlation between advanced stage disease, high MYCN expression levels, and elevated expression of genes involved in ribosome biogenesis in several large neuroblastoma patient cohorts." (PMID 30542116, 2019). "Unexpectedly, we observed very low overall survival and event free survival (EFS) rates in neuroblastomas with 2p gain, which were comparable with patients with MYCN amplification." (PMID 31649880, 2019). "It was reported that MYCN expression was required to activate the differentiation in neuroblastoma cells." (PMID 31396265, 2019). "The result showed that it negatively correlated to relapse-free survival probability significantly in patients with neuroblastoma with non-MYCN amplified tumor." (PMID 31489113, 2019). "MYCN serves as an oncogenic regulator that mediates aberrant signaling pathways and leads to HR neuroblastoma." (PMID 31624245, 2019). "MYCN-amplified (MNA) neuroblastoma increases cell growth by glutamine transport and metabolism enhancement, thus depletion of glutamine causes the limitation of TCA cycle intermediates and eventually cell death." (PMID 31624245, 2019). "In conclusion, these data demonstrate that α-N-catenin is a tumor suppressor in non-MYCN-amplified neuroblastomas and it inhibits NF-κB signaling pathway to suppress tumor growth in human neuroblastomas." (PMID 31489113, 2019). "Another example is AT7519 following the finding that inactivation of CDK2 is synthetically lethal to MYCN in neuroblastoma cells." (PMID 35582571, 2019). "Studies in zebrafish have shown that forced MycN expression in sympathoadrenal precursor cells blocks the development of chromaffin cells leading to the development of neuroblastoma." (PMID 30760980, 2019). "We previously demonstrated that inhibition of FAK decreased neuroblastoma cell survival, migration, invasion, and metastases using long-term passage neuroblastoma cell lines with MYCN amplification." (PMID 31519958, 2019). "To further explore how the RNA pol I inhibitors influence the biology of MYCN-amplified neuroblastoma cells, we examined the effect of quarfloxin and CX-5461 on MycN expression in several different MYCN-amplified neuroblastoma cell lines." (PMID 30542116, 2019). "CX-5461 repressed the growth of established MYCN-amplified neuroblastoma xenograft tumors in nude mice." (PMID 30542116, 2019). "The amplification or overexpression of MYCN represent a major genetic defect and accounts for the poor prognosis of neuroblastoma." (PMID 30741995, 2019).
neuroblastoma (continued). "In particular, our findings indicating that loss of Casp2 impacts neuronal differentiation, is likely a key contributor to delaying neuroblastoma onset and reduced adrenal tumor development in Th-MYCN/Casp2−/− mice." (PMID 30670683, 2019). "Out of the seven T-UCRs, three were randomly selected (uc.279, uc.364, and uc.460) to be evaluated for expression in a neuroblastoma cohort (n = 366), which led to finding significant upregulation in two of the T-UCRs (uc.279, uc.460) in MYCN-amplified tumors." (PMID 31167408, 2019). "Together these data strongly suggest that increased and sustained expression of MycN in cells within the neural crest is sufficient for neuroblastoma development and establish MYCN as a major oncogenic driver in neuroblastoma." (PMID 30760980, 2019). "The genes survivin and insulin growth factor 2 binding protein 1 within this chromosomal region have been shown to promote neuroblastoma cell survival and increase MYCN mRNA expression, respectively." (PMID 31346162, 2019). "It was first identified in neuroblastoma cells, and about 22% of neuroblastoma patients have abnormal amplification in MYCN." (PMID 31443513, 2019). "Inhibition of the bromodomain and extraterminal domain (BET) family has also been shown to down-regulate MYCN transcription in MYCN-amplified neuroblastoma." (PMID 35582571, 2019). "A review of relapsed stage 4 patients in the International Neuroblastoma Risk Group (INRG) database from 1990 to 2002 revealed 5-year OS of 8% and 4% for MYCN amplified disease." (PMID 30822684, 2019). "In an orthotopic xenograft mouse model of human neuroblastoma, the MYCN-amplified neuroblastoma cell line IMR32 metastasizes to many distant organs, in contrast to single-copy MYCN neuroblastoma cells." (PMID 30836897, 2019). "Neuroblastoma, a highly malignant childhood tumor of the sympathetic nervous system, is frequently characterized by MYCN gene amplification and high expression of MYCN and c-MYC signature genes." (PMID 30542116, 2019). "Recently, a set of self-regulated master transcription factors known as the “core transcriptional regulatory circuits” have been described to maintain MYCN-amplified neuroblastoma in a state of pro-growth and pro-survival." (PMID 35582571, 2019). "In particular, while caspase-2 deficiency augments lymphoma development in the EμMyc mouse model, it leads to delayed neuroblastoma development in Th-MYCN mice." (PMID 30670683, 2019). "Abnormal amplification of MYCN is considered an important indicator of poor prognosis for neuroblastoma." (PMID 31443513, 2019). "MYCN has been closely tied to the regulation of neuroblastoma cell growth, and confers the serine-glycine-one-carbon pathway to promote metabolic reprogramming in HR neuroblastoma." (PMID 31624245, 2019). "SHEP-TET21N is a MycN-inducible cell line derived from the parental single-copy MYCN human neuroblastoma cell line SHEP." (PMID 30542116, 2019). "MYCN is known to activate the TERT gene and the MYCN amplification is the most frequent genomic alteration in neuroblastoma." (PMID 31285550, 2019). "At the same time, there was an accumulation of lipid droplets in neuroblastoma cells which were treated with MYCN-inhibitors, suggesting a potential role for lipid metabolites involved in tumor regression." (PMID 31620124, 2019).
neuroblastoma (continued). "Lin28B-mediated downregulation of Let-7 miRNAs increases MycN expression and targeted ectopic expression of Lin28B in mouse neural crest cells results in MycN-driven neuroblastoma." (PMID 30760980, 2019). "IMR-32 cells were used in this study as a human neuroblastoma cell line with MYCN gene amplification." (PMID 31452837, 2019). "MYCN is an important proto-oncogene, whose amplification is abnormal in more than one-fifth of neuroblastoma patients." (PMID 31443513, 2019). "The majority of patients with neuroblastoma due to MYCN oncogene amplification and consequent N-Myc oncoprotein over-expression die of the disease." (PMID 31690716, 2019). "The c-MYC homolog MYCN (encoding the transcription factor N-MYC), a proto-oncogene, was originally isolated from neuroblastoma cells." (PMID 31396265, 2019). "Together, these data suggest that inhibition of ribosome biogenesis in neuroblastoma should be tested as a treatment option for neuroblastoma patients expressing high levels of MycN and/or c-Myc." (PMID 30542116, 2019). "In this study, we investigated the effects of low PRMT1 levels on a non-MYCN amplified neuroblastoma SK-N-SH cell line." (PMID 30741995, 2019). "Here, we demonstrate that inactivation of β1-integrin by FNIII14 induced proteasomal degradation in N-Myc of human neuroblastoma cells with the MYCN gene amplification." (PMID 31452837, 2019). "Compared with MYCN single-copy neuroblastoma cells, DHA level was significantly lower in MYCN-amplified neuroblastoma cells." (PMID 31856871, 2019). "A recent study suggests that “enhancer invasion” shapes MYCN-dependent transcriptional upregulation in neuroblastomas with MYCN gene amplification." (PMID 31819055, 2019). "This molecule was found to have specific activity against MYCN target genes, which correlated with high level MYCN expression and MYCN amplification in a panel of neuroblastoma cell lines." (PMID 35582571, 2019). "The expression of MYCN in IMR32 cells is 33 times higher than in single-copy MYCN neuroblastoma cell lines such as SK-N-SH." (PMID 30836897, 2019). "Polymorphic alleles within the lin-28 homolog B (LIN28B) locus have been linked to neuroblastoma development and deregulated expression of LIN28B induces expression of MycN." (PMID 30760980, 2019). "Next, we used two different siRNAs targeting MYCN to knockdown MycN expression in the MNA neuroblastoma cell line IMR-32." (PMID 30542116, 2019). "Here, we investigated the relationship between shear stress and cell motility in the MYCN-amplified human neuroblastoma cell line IMR32, using a microfluidic device." (PMID 30836897, 2019). "Here, we identified DHA as the strongest upregulated FA after MYCN depletion and validated the tumor suppressive properties of DHA in highly malignant MYCN-amplified neuroblastoma cells." (PMID 31856871, 2019). "The expression level of ELOVL2 in neuroblastomas from the 496-tumor cohort was significantly correlated with MYCN status." (PMID 31856871, 2019). "Here, we demonstrate that inactivation of β1-integrin by FNIII14 induced proteasomal degradation in N-Myc of neuroblastoma cells with MYCN amplification." (PMID 31452837, 2019). "Some effort has been made in the recent years to inhibit MYCN in these tumors, however, most of them were adapted from approaches that have been identified in research conducted originally in neuroblastoma." (PMID 35582571, 2019). "Neuroblastoma cells expressing high levels of MYCN or c-MYC were significantly more sensitive to treatment with these compounds." (PMID 30542116, 2019). "Preferential sensitivity to inhibitors of PI3K/mTOR, including NVP-BEZ235, were prominently identified in a chemical-genetic screen of isogenic neuroblastoma cells with genetically modified MYCN stabilization versus wild-type MYCN expression." (PMID 35582571, 2019). "MYCN plays a critical role in neuroblastoma tumor initiation, aggressiveness and resistance to chemotherapy." (PMID 31856871, 2019).